BRCA2 (BRCA2 DNA repair associated)
Diseases named in the same sentence as BRCA2 in open-access papers (continued):
Sharing a sentence is not in itself a finding about the gene and the disease.
cancer (continued). "Thus, combining PARP1 and RAD52 inhibitors to treat BRCA1 or BRCA2 mutant cancers might provide little or no therapeutic gain, and might increase normal tissue toxicity." (PMID 29145865, 2017). "In addition, to expand the in vitro data showing lack of olaparib sensitization in non-cancer HK-2 cells, an in vivo study using an siRNA targeting the mouse sequence of BRCA2 will be necessary to elucidate the potential effects of BRCA2 inhibition on olaparib sensitivity in normal tissues." (PMID 26959114, 2016). "The findings that FOXM1B induces DNA repair genes such as XRCC1 and BRCA2 and the fact that most cancers contain genomic instability suggest that activation of DNA repair and genomic instability may not be mutually exclusive in cancer cells." (PMID 19287496, 2009). "CBC was the commonest cancer in all groups (BRCA1 PV carriers: 66 events, BRCA2 PV carriers: 43 events, noncarriers: 237 events)." (PMID 39475295, 2025). "More precisely, cancer cells lacking the repair proteins BRCA1 and BRCA2 rely more heavily on PARP to repair their damaged DNA." (PMID 41347092, 2025). "We lacked specific cancer incidence data following RRSO and/or RRM for non-BRCA CSG carriers and assumed these were similar to BRCA1 and BRCA2 estimates." (PMID 38334999, 2024). "This quandary leads one to formulate the logical hypothesis that cancer cells must first, or at least simultaneously, acquire accompanying epigenetic and/or genetic modifications that enable normal cells to survive without BRCA2 and eventually transition to malignancy." (PMID 38557488, 2024). "Differences in the number of cancer types and cancer-affected members among relatives between BRCA1 and BRCA2 carriers, however, were not significant." (PMID 36861435, 2023). "There is a lot of research on the psychological determinants of the motivations of women to engage in cancer-preventive behaviors and specifically in BRCA1- and BRCA2-related cancer prevention, but there is still not enough information on men’s motivations." (PMID 35303741, 2022). "LUAD1 enriched for alterations in EGFR, MN1 and MYH9, LUAD2 enriched for BRCA2, while LUAD3 did not enrich for known cancer drivers." (PMID 35383171, 2022). "Further molecular studies on family members were not performed, although multiple cancers of the Li-Fraumeni and BRCA1/BRCA2-spectrum were referred in the maternal family history." (PMID 36003761, 2022). "This group included 66 (22.7%) with a known PDAC PGV (54 BRCA2, 5 PALB2, 5 ATM, 2 BRCA1) previously identified outside the MDPC on the basis of personal or family history of other cancer diagnoses, but no known PDAC family history." (PMID 35906821, 2022). "Despite the modest sample size, we observed signficantly higher pCR rates in patients with BRCAmut cancers, but not BRCA1meth cancers, than in those with either BRCA1 and BRCA2 proficient cancers (P = 0.033)." (PMID 35857626, 2022). "The positive predictive value (PPV) of the prostate biopsy—number of cancers found divided by the number of biopsies—when PSA was >3.0ng/ml was 48% in BRCA2 carriers, 33.3% in BRCA2 non-carriers, 37.5% in BRCA1 carriers and 23.3% in BRCA1 non-carriers." (PMID 34884434, 2021). "During the last three years also deep sequencing data on solid cancer unveiled unexpected germline gene aberrations in neuroendocrine neoplasia (e.g., MUTYH, CHEK2, and BRCA2 genes in pancreas NEN) together with a substantial absence of known cancer drivers." (PMID 32869113, 2021). "Though governmental cancer care insurance covers for BRCA1 and BRCA2 testing, it does not cover the major part of the reconstruction surgery." (PMID 32733560, 2020). "Although family and personal history are also utilized as part of decisions of when to recommend elevated cancer surveillance, BRCA1 and BRCA2 VUS identified in genetic screens do not inform such decisions." (PMID 30832243, 2019).
cancer (continued). "Regarding BRCA1 and BRCA2, both of these genes showed similar strong positive correlations with UBE2C in different cancers, but a negative correlation was observed for BRCA1 in THCA and for BRCA2 in TGCT." (PMID 31067633, 2019). "These DSBs that normally would be repaired by HR with the sister chromatid duplex would be fixed inefficiently in certain cancers due to the absence of any one of the three key HR repair proteins BRCA1, BRCA2, or PALB2." (PMID 29998112, 2018). "In the third stage, we focused on enriching pools of barcoded libraries of HapMap individuals for non-repeat-masked regions of two clinically relevant human cancer genes (BRCA1 and BRCA2)." (PMID 22913592, 2012). "RAD21 expression correlated with shorter survival in BRCA2 (P = 0.006) and BRCAX (P = 0.008), but not BRCA1 cancers (P = 0.713)." (PMID 22537934, 2012). "The expression of BRCA2 protein in the PBL of HNSCC patients also declined significantly to 71% of the level in PBL of controls and exhibited a significant negative correlation with cancer stage." (PMID 37113717, 2023). "Interestingly, RAD21 expression correlated with shorter survival in BRCA2 (p = 0.006) and BRCAX (p = 0.008), but not BRCA1 cancers (p = 0.713)." (PMID 35740618, 2022). "Interestingly, almost one third of MBC patients, who were carriers of P/LPVs in BRCA1 or BRCA2, had no family history of other HBOC-related cancers in their first- and/or second-degree relatives." (PMID 33891299, 2021). "However, among 26 men who were affected with first BC, 42% did not have any relatives with cancer (11/26; 2 BRCA1 and 9 BRCA2; P = 0.56)." (PMID 34575694, 2021). "Furthermore, another 37yo patient (#3227) carried a VUS in BRCA2 (c.8386C > T), while having Luminal A-HER-2 negative BC and no cancer family history." (PMID 34011307, 2021). "Given the pronounced sensitivity to CuET in tumor cell lines lacking the genome integrity caretaker proteins BRCA1 and BRCA2, here we investigated the impact of NPL4 targeting by CuET on DNA replication dynamics and DNA damage response pathways in human cancer cell models." (PMID 32085572, 2020). "Interestingly, high RAD21 expression correlated with poorer survival in BRCA2 (P = 0.006) and BRCAX cancers (P = 0.008), but not in BRCA1 cancers (P = 0.71)." (PMID 22537934, 2012). "However, there is some evidence that cancer biology is different in BRCA1 carriers compared to non-carriers, with BCRA1 carriers having lower or higher and BRCA2 carriers having higher survival rates, which would result in an over- or under-estimation of the ICER, respectively." (PMID 37365514, 2023). "From the genes evaluated here, BRCA1, BRCA2, and PALB2 are part of the ACMG Secondary Findings v3.0 list and laboratories are now recommended to report GPV in these genes even in individuals without a personal or family history of cancer when next generation sequencing is performed." (PMID 35805029, 2022). "A reasonable explanation is that, on average, BRCA2-related cancers (like BRCA1-related cancers) have a faster doubling time than sporadic cancers, which increases their likelihood of presenting as palpable interval cancers rather than being detected on the next round of screening." (PMID 30513626, 2018). "Although there are no clinically meaningful prognostic or predictive cancer biomarkers available, a series of potential biomarkers have been identified, for example, in the blood (VEGF), on the cell surface (epithelial growth factor receptor 1 (EGFR)), and in the cell nucleus (BRCA1, BRCA2)." (PMID 29138528, 2017).
tumor (1,682 papers, 1995 to 2026). "The concept — that the loss of BRCA1 or BRCA2 can act as a trigger for cell death and thereby contribute to tumor suppression — has been proposed previously." (PMID 40841483, 2026). "BRCA1 mutations were associated with CD8+ Trm expansion, whereas BRCA2 mutations were linked to tumor CD4+ Trm expansion and peripheral T/NK cell cytotoxicity." (PMID 42189716, 2026). "Another patient, treated with first‐line palliative chemotherapy who was eventually diagnosed with a BRCA2‐mutated tumour and switched to PARP‐inhibitor, was also excluded from the survival analyses." (PMID 41392017, 2026). "BRCA2 is a tumor suppressor gene involved in DNA repair, and its mutation raises the possibility of an alternative genetic pathway contributing to the development of ND." (PMID 40723533, 2025). "BRCA2-deficient MB cells were also shown to upregulate G4 helicases to foster tumor cell proliferation." (PMID 40854122, 2025). "The inhibition of PARP activity has been shown to exert antitumor effects in tumours harbouring BRCA1 or BRCA2 mutations and exhibiting homologous recombination deficiency." (PMID 40337291, 2025). "Genomic profiling of OSCC samples has identified occasional BRCA1 and BRCA2 mutations, suggesting their contributions to tumor onset and progression." (PMID 40224184, 2025). "PARP inhibitors are also approved in the treatment of BRCA2-deficient tumours: however, mechanisms of PARPi resistance differ substantially compared to cells lacking BRCA1." (PMID 39994444, 2025). "Of the 40 cases with WGS and derived mutational signatures, the 3 cases with the highest levels of signature 3 (accounting for 33.8%–38.8% of the tumor’s somatic variants) included the 2 cases with a pathogenic germline BRCA2 variant." (PMID 40072012, 2025). "Comprehensive tumor molecular profiling identified a pathogenic BRCA2 mutation (c.5291C>G; p.Ser1764*, with loss of the wild-type allele), which was confirmed to be a germline alteration through germline testing." (PMID 41487567, 2025). "In vivo, V66-exatecan ADC exhibited remarkable efficacy against BRCA2-deficient xenografts, with significant tumor regression observed in treated animals." (PMID 41077566, 2025). "The BRCA2 variant is a known carcinogenic tumor suppressor gene biomarker that normally involves DNA replication machinery." (PMID 41471728, 2025). "Lesion-by-lesion analysis revealed significant differences in [18F]-FTT uptake by primary tumor type (P < 0.001) and higher uptake in lesions with BRCA2 mutations (n = 65) than in lesions with other genetic mutations (n = 26) (6.7 vs. 5.5, P = 0.03)." (PMID 41251745, 2025). "The second patient with the BRCA2 methylation in her primary tumor as well as the associated xenograft tissue is also a young patient who was diagnosed with a TNBC at the age of 29, during her second pregnancy." (PMID 39392573, 2025). "The concordance rate for BRCA2 variants was 68.8%, with 11 out of 16 P/LPGVs identified on tumor genomic profiling." (PMID 41465149, 2025). "When the mutational signature analysis was updated using COSMIC v325, the tumor with an elevated signature 3 had 2 deleterious germline variants in the HR pathway (BRCA2/FANCE)." (PMID 40072012, 2025). "It demonstrates that BRCA2-associated HGSOCs have a higher rate of complete tumor cell elimination upon NACT when compared to BRCA1-mutated tumors." (PMID 40547808, 2025). "Despite the homogeneous tumor presence of BRCA2 LOH, the MLH1/PMS2-deficient region exhibited a higher mutation burden, potentially indicating a distinct tumor evolutionary trajectory." (PMID 40076915, 2025). "In vivo studies showed efficient tumor targeting and significant survival benefits, with the most pronounced therapeutic effect observed in BRCA2-deficient tumors." (PMID 41077566, 2025). "BRCA2 is a tumor suppressor that exhibits recessive behavior, and the wild type allele is typically lost by tumor cells during the loss of heterozygosity process." (PMID 40136510, 2025).
tumor (continued). "Genomic analysis of the tumor tissue revealed a high allelic frequency (VAF~90%) of the BRCA2 variant c.8693_8695delinsGT, which is indicative of LOH." (PMID 40076915, 2025). "The proportion of tumor BRCA1 or BRCA2 variants in tumor tissue was significantly lower in the AKT pathway-altered group (8.0 vs. 16.2%, p < 0.001)." (PMID 39466567, 2025). "In 2005, two landmark studies demonstrated that tumor cells deficient in BRCA1 or BRCA2 exhibit selective sensitivity to small-molecule inhibitors of the PARP family." (PMID 40830526, 2025). "While only 5–10% of cases are hereditary, primarily linked to germline mutations in the BRCA1 and BRCA2 genes, the majority are sporadic, caused by the accumulation of somatic mutations over time, leading to uncontrolled cell growth and tumor development." (PMID 40004528, 2025). "This establishes a tightly coupled self-reinforcing loop that creates a cycle of mutagenesis and genome instability that potentially drives tumor initiation and shapes the mutational landscape of BRCA2-mutant tumors." (PMID 41162355, 2025). "The model revealed that BRCA1 mutations were associated with higher inflammatory infiltration and necrosis, as well as off‐center nuclei and pushing tumor margins, while BRCA2 mutations were associated with more active mitotic phases." (PMID 40439693, 2025). "Large population-based studies have also established an increased risk for BRCA2 carriers of early-onset disease, higher tumor grade and metastatic presentation, whereas other DDR genes exhibit more heterogeneous and gene-specific penetrance." (PMID 41595443, 2025). "Next, we wanted to assess the potential of combining SM08502 with olaparib to inhibit tumor progression in an established BRCA2-mutated olaparib-resistant PDX model, PDX-GTFB1016-OR, in immunodeficient mice." (PMID 41340358, 2025). "BRCA1 and BRCA2 genes were discovered in 1994 and 1995, respectively, that their encoding proteins involved in tumor suppression, regulating cell replication, DNA damage repair, and normal cell growth in the human body." (PMID 40104509, 2025). "Despite an initial FIGO IVB classification and high tumor burden, she achieved prolonged remission, highlighting the known impact of optimal cytoreductive surgery, platinum sensitivity, BRCA2 mutation status, and anti-VEGF therapy." (PMID 41367869, 2025). "In summary, the analysis of distinct MLH1/PMS2-expressing tumor regions from a patient with a novel de novo BRCA2 variant provided valuable insights into the evolution of OC." (PMID 40076915, 2025). "This poor prognostic factor is associated with germline BRCA2 mutations, other homologous recombination repair gene mutation (HRRm), and tumor suppressor genes alterations." (PMID 39937427, 2025). "This leads to genomic instability in BRCA2-deficient tumor cells, resulting in increased tumor cell death." (PMID 39759116, 2025). "As we report in the case presentation, we can assert that the nonsense BRCA2 alteration is germline because we also investigated the non‐tumoral tissue and found the same nonsense BRCA2 variant (p.S1882*) as that found in the corresponding tumor." (PMID 40205657, 2025). "As a key HRR pathway gene, BRCA2 mutation causes homologous recombination repair defects, making tumor cells dependent on PARP-mediated single-strand repair." (PMID 40823097, 2025). "Real-world database analyses suggest that BRCA1 or BRCA2 pathogenic variants are associated with increased PDL1 expression on tumor and immune cells and that biallelic inactivation correlates with the highest TMB." (PMID 40426860, 2025).
tumor (continued). "A germline BRCA2 mutation was inferred through tissue-based gene panel testing on a tumor sample, using variant allele frequency analysis." (PMID 40065879, 2025). "In germline pathogenic variant carriers, the location of mutations within BRCA1 or BRCA2 or the retention of the wildtype allele in the tumor can result in a hypomorphic phenotype associated with resistance to platinum-based therapy." (PMID 41255967, 2025). "Olaparib inhibits polyADP ribose polymerase (PARP), blocking repair and enhancing cell death in BRCA1- or BRCA2-deficient tumours." (PMID 41020877, 2025). "Case studies have shown concordant BRCA2 mutations in both epithelial and sarcomatous tumor components supporting a monoclonal origin and the theoretical responsiveness of both compartments to PARP inhibition." (PMID 41584593, 2025). "In contrast, the ID8 isogenic model, with specific Brca1 and Brca2 mutations, reflected patient tumour‐like responses to PARP inhibitor monotherapy and combination therapy." (PMID 40977519, 2025). "Reduced expression and loss of BRCA2 activity lead to neoplasm and transformation due, in part, to the accumulation of replication-associated deleterious events whose origins are not well-defined." (PMID 38830843, 2024). "Our previous results show that BRCA2-deficient cells promote tumor development by inactivating the SAC, and that PP2Ais can reactivate the SAC." (PMID 37934606, 2024). "Additional investigation of our HR expression signature in independent CPTAC8 and TCGA9 HGSOC tumor cohort data showed a high quantitative correlation to BRCA1 or BRCA2 mutational status." (PMID 38480868, 2024). "Somatic BRCA mutations were defined as either a BRCA1 or BRCA2 mutation present only in the tumor tissue." (PMID 38540206, 2024). "In fact, BRCA1 and BRCA2 mutated cells are more responsive to anti-tumor treatments that induce the accumulation of damage to the DNA double strand, the so-called PARP-inhibitor." (PMID 39335746, 2024). "A BRCA2 c.3860del, p.(Asn1287IlefsTer6) variant (known to be a germline variant and present in ClinVar with 24 entries) was identified by tumor-only comprehensive genomic profiling, with a variant allele frequency of 20.7%." (PMID 39363506, 2024). "How these BRCA2-deficient tumor cells survive despite accumulating DNA damage and abnormal mitosis is not fully understood, and this lethality must be overcome during tumorigenesis." (PMID 37934606, 2024). "It is crucial to understand the pathogenetic mechanisms underlying the mutations in the BRCA1 and BRCA2 genes and how these are qualitatively and quantitatively linked to the risk of developing pre-tumour lesions like STIC and gynaecological cancers." (PMID 39594243, 2024). "HR deficiency is often driven by loss of BRCA1, BRCA2 or PALB2 function in tumor cells, which is the result of inactivating mutations and LOH." (PMID 38589664, 2024). "In BRCA1 and BRCA2 mutated tumor cells, the HRD activity was compromised; therefore, the collapsed replication forks are unable to be repaired, and cell death occurs." (PMID 39335746, 2024). "In a study looking at BRCA2 reversion mutations in mCRPC, a large genomic database identified 24 gBRCAm patients out of 1534 mCRPC patients undergoing circulating tumour DNA (ctDNA) testing." (PMID 39796639, 2024). "We demonstrated the significance of their genetic interaction by the lethality of Brca2-mutant mice and inhibition of Brca2-deficient tumor growth in mice by Mlh1 loss." (PMID 38271119, 2024).